IL22 (interleukin 22)
Diseases named in the same sentence as IL22 in open-access papers (continued):
Sharing a sentence is not in itself a finding about the gene and the disease.
psoriasis (continued). "Subsequent studies revealed CD4-positive T cells with IL-22 and CD8-positive T cells producing IL-17 remained resident in previously involved psoriasis lesions after complete clinical resolution from a variety of treatments." (PMID 32276410, 2020). "Clinical skin severity was assessed with the psoriasis area index (PASI), whilst ELISA detected the expression of TNF-α, IL-17A, and IL-22." (PMID 33253155, 2020). "A direct IL-22-neutralizing antibody, ILV-094, has completed Phase I and II trials for psoriasis and rheumatoid arthritis, respectively." (PMID 33042126, 2020). "IL-38 is highly expressed in mouse skin, and IL-36 procytokines and IL-36Ra mRNA levels are increased in various mouse models of psoriasis, with elevated levels of IL-1β, IFN-γ, IL-17, and IL-22, among others." (PMID 31387327, 2019). "Hence, IL-22 may collaborate with other soluble factors and cells together forming inflammatory circuits that otherwise exist as constitutive or inducible pathways in normal skin and become pathologically amplificated in psoriasis." (PMID 30291393, 2019). "Our results showed that IL-21R is highly expressed in PBMCs and in the lesional skin of psoriasis patients, and that IL-21 can promote CD4+ T cell proliferation and Th17 cell differentiation and also the secretion of IL-17A and IL-22." (PMID 31440249, 2019). "The mRNA levels of IL-21, IL-21R, IL-17A, IL-22, IL-23, RORγt, and IFN-γ were increased, whereas the mRNA level of Foxp3 was decreased in the PBMCs of psoriasis patients." (PMID 31440249, 2019). "The expressions of crucial inflammatory mediators (including IL-1β, IL-2, IL-6, IL-10, IL-17, IL-22, IL-23, IFN-γ, TNF-α) in skin tissues were measured by ELISA due to the import role of inflammatory cytokines in psoriasis." (PMID 31181689, 2019). "The mRNA levels of IL-17A, IL-22, IL-23, RORγt, and IFN-γ were increased in the lesional skin of psoriasis patients, whereas Foxp3, a vital transcriptional factor of Treg cells, was decreased in psoriasis patients." (PMID 31440249, 2019). "After silencing IL37, cells were stimulated with a mixture of five cytokines designated as M5 (IL-1α, IL-17A, IL-22, Oncostatin M, and TNF-α) to mimic the microenvironment of keratinocytes in psoriasis." (PMID 30918469, 2019). "The Interleukin-23 (IL-23)/IL-17/IL-22 cytokine axis, TNF-α, and IL-1β are important inflammatory mediators in the pathogenesis of psoriasis." (PMID 31252620, 2019). "Additionally, IL-22 may have a very important role in the triggering of psoriasis." (PMID 31275060, 2019). "Studies from Dr. Wang’s group has established an essential role of T cell-derived cytokines, including IFNγ, IL17A and IL22, in maintaining KRT6/16 and KRT17 expression in the chronic lesion of psoriasis." (PMID 31374826, 2019). "Flow cytometry analysis revealed a shared increase in the percentage of CD4+ T regulatory cells in all psoriasis subtypes relative to controls, whereas distinct psoriasis subtypes displayed differences in IL-17A, IFN-gamma, and IL-22 production." (PMID 30054515, 2018). "In an in vitro study using reconstituted human epidermal sheets, IL-17A stimulated greater transcriptional activation than IL-22 or IFN-γ, correlating with the psoriasis transcriptome." (PMID 30109481, 2018). "The involvement of these cytokines in psoriasis has also been revealed through the therapeutic silencing of key immune system components, such as TNF-α, IL-17, IFN-γ, IL-22, and the Th17/IL-23 axis." (PMID 29679037, 2018). "Our present study shows that IL-23 acts directly on macrophages to induce IL-17A, IL-17F, IL-22 and IFN-γ productions which likely promote the severity of psoriasis-like dermatitis in mice." (PMID 29508278, 2018). "In a recent publication, a subset of myeloid cells expressing CD5 promoting induction of IL-22, IFNγ, TNF, and granzyme B in mixed lymphocyte reaction assays was enriched in psoriasis epidermis." (PMID 29520279, 2018).
psoriasis (continued). "Based on the knowledge that SCCA molecules are highly expressed in psoriatic skin and that SCCAs are downstream molecules of IL-22/IL-17 tightly correlated with pathogenesis of psoriasis, we explored the usefulness of SCCA2 as a biomarker for psoriasis." (PMID 29642409, 2018). "Interestingly although IL-22 plays a protective role in mucosal diseases such as inflammatory bowel disease by enhancing barrier integrity of the intestinal tract, in other diseases such as psoriasis it has been eluded to synergise with proinflammatory cytokines and induce disease progression." (PMID 29311948, 2017). "NHEK were stimulated by A-SAA or the cytokines IL-1α, IL-17A, IL-22, OSM, TNF-α alone or in combination, previously reported to reproduce features of psoriasis." (PMID 28708859, 2017). "Cytokine and chemokine expression levels in the mouse skins were also determined because expressions of IL-6, IL-17, IL-22, CCL20 and CXCL1 were involved in the pathogenesis of psoriasis." (PMID 29138509, 2017). "A high expression of IL-22 in various inflammatory disorders, that is, rheumatoid arthritis, IBD, and psoriasis, has been reported by a number of researchers." (PMID 28050571, 2016). "The importance of TYK2 in inflammatory diseases is based on genetic polymorphisms and murine experiments with knockout mice demonstrating its role in IL22 and IL23-mediated signaling in psoriasis." (PMID 27711196, 2016). "The data shown in our study revealed that inflammatory cytokines in plasma including IL-17A, IL-17 F, IL-22 and IL-23 were reduced with the attenuation of IMQ-induced psoriasis-like inflammation in the H and L group mice." (PMID 27581210, 2016). "Although the pathogenesis of psoriasis is not fully understood, evidence suggests that many cytokines, including IL-6, IL-17A, IL17F, IL-22, IL-23 and TNF-α, are involved and interact as a network in the pathogenesis of psoriasis." (PMID 27581210, 2016). "T helper (Th) cells producing interleukin (IL)-17, IL-22, and tumor necrosis factor (TNF) form the key T cell population driving psoriasis pathogenesis." (PMID 27158469, 2016). "The crucial role of ILC3 subpopulations in psoriasis pathogenesis is supported by the finding that Rorγt+CD56+ ILC3, which are capable of producing IL-22, are highly accumulated in the skin of patients with psoriasis." (PMID 27158469, 2016). "Taken together, various types of immune cells produce the psoriasis-driving cytokines TNF, IL-17A, and IL-22." (PMID 27158469, 2016). "Our attempt to model skin inflammation showed that the combination of IL-17A, IL-22, IL-1α, OSM and TNFα (Mix M5) synergistically increases chemokine and antimicrobial-peptide expression, recapitulating some features of psoriasis." (PMID 25010647, 2014). "Serum LL-37 levels were significantly correlated with serum IL-22 and IFN-γ levels in patients with psoriasis." (PMID 25197165, 2014). "IL-12(p40), IL-22, and IFN-γ were significantly and positively correlated with PASI in all patients with psoriasis." (PMID 25197165, 2014). "In addition, specific cytokines, such as IL-22, can trigger regenerative and proliferative programs in keratinocytes as well as induce antimicrobial peptides, and hence can be centrally involved in the pathogenesis of skin diseases characterized by epidermal hyperproliferation, including psoriasis." (PMID 25226283, 2014). "Many immune-derived cytokines, including IL-23, IL-17A, IL-20, IL-22, IL-1β, IL-6, and TNF-a, are involved and interact as a network in the pathogenesis of psoriasis." (PMID 23825622, 2013). "For CD8+ T cells, we observed that the production of IL-17A, IL-22, IFN-gamma, TNF-alpha, and IL-2 were higher in lesional skin than unaffected skin of psoriasis patients." (PMID 23468834, 2013). "In patients suffering for psoriasis, biopsies of injured skin show a high number of Th17 and high levels of TGF-β1, IL-6, IL-15, IL-17, IL-22, and IL-23." (PMID 23971052, 2013).
psoriasis (continued). "Increased IL22 from activated TH22 cells was demonstrated in the blood of RA patients and in the skin of psoriasis patients." (PMID 23840241, 2013). "Although psoriasis was initially classified as a Th-1-polarized disease, a clear role for CD4+ T cells that produce IL-17A and IL-22 (Th-17 and Th-22 cells) has been established in recent years, primarily at lesional sites, but also in the blood." (PMID 23468834, 2013). "In psoriasis, IFN-gamma, the prototype Th-1 cytokine, interplays with IL-2, TNF-alpha, IL-17, and IL-22 to contribute to inflammation and altered differentiation." (PMID 23468834, 2013). "IL-22, along with IL-17, induces STAT3 activation and cytokine/chemokine production, showing that way, an important role in the physiopathology of psoriasis." (PMID 23213332, 2012). "Therefore, we hypothesized that IL-22 may be a key cytokine of the K17/T cell/cytokine autoimmune loop and induce K17 expression by activating specific signaling pathways, and thereby participate in the development of psoriasis." (PMID 22808266, 2012). "In addition, the Th17 cytokines IL-17 and IL-22 have synergetical effect as psoriasis-related cytokines, and the synergism of inflammatory cytokines may be an important process of the pathogenesis of psoriasis." (PMID 22808266, 2012). "Psoriasis is characterized by the upregulation of the cytokines IFN-α, IFN-γ, TNF-α, IL-17, IL-22, and IL-23, while TNF-α, IFN-γ, and Th17+ T cells have been shown to be important in HIV-1 controllers." (PMID 22577363, 2012). "We demonstrated that psoriasis-related transcripts, such as IFN-γ, TNF-α, IL-17A, CCL20, IL-23, IL-6, IL-1α and IL-22, were significantly enhanced in mouse ears treated with PL and rMCP-1 than those with 1×PBS control." (PMID 21311769, 2011). "We therefore evaluated the expression of selected cytokines and chemokines thought to contribute to initiation or maintenance of the inflammatory cascade in human psoriasis (e.g., TNF, IL22, IL6, CXCL1)." (PMID 21483750, 2011). "Additionally, we identified distinct T cell expression patterns across disease states, including characteristic expression of IL13 and IL22 in AD, IL17 family genes in psoriasis, and IFNG in granuloma annulare (GA)." (PMID 40537825, 2025). "Further validation by RT-PCR confirmed that IL-23 directly acted on macrophages, promoting the levels of IL-17A, IL-17F, IL-22, and IFN-γ, which may contribute to the severity of psoriasis in mice." (PMID 41383588, 2025). "Interestingly, the psoriasis-related inflammatory factors, including TNF-α, IL-17, IL-22, OSM, and IL-1α, promoted YAP1 up-regulation in keratinocytes, as indicated by increased YAP1 expression (& f)." (PMID 40108109, 2025). "In psoriasis, dendritic cells secrete interleukin-12 (IL-12) and IL-23, while Th1 cells secrete tumor necrosis factor-alpha (TNF-α) and interferon-gamma (IFN-γ), and Th17 cells secrete interleukin-17 (IL-17) and interleukin-22 (IL-22)." (PMID 40585669, 2025). "The data suggest that subcutaneous administration of exosomes derived from hUCB-MSCs preconditioned with IL-17, IL-22, and TNF-α has therapeutic potential for treating skin inflammation and could be applied in psoriasis treatment." (PMID 40906403, 2025). "Central to the pathogenesis of psoriasis are dysregulated immune responses mediated by dendritic cells, Th1, Th17, and Th22 lymphocytes, and the overproduction of cytokines such as TNF-α, IL-17, IL-23, and IL-22." (PMID 40690118, 2025). "In psoriasis, chronic inflammation, particularly mediated by IFN-γ, IL-17A, and IL-22, may override any anti-proliferative effect of EPPK1 loss." (PMID 40746860, 2025). "Similarly, in psoriasis, CD4+ T cells are activated by dendritic cells presenting self-antigens, releasing proinflammatory cytokines such as TNF-α, IL-17, and IL-22." (PMID 40310305, 2025).
psoriasis (continued). "Furthermore, in an in vitro psoriasis model where normal keratinocytes were stimulated with the M5 cytokine cocktail (TNF-α, IL-17A, IL-22, IL-1α, and oncostatin M), DGAT2 expression was similarly reduced." (PMID 40694426, 2025). "Notably, the module score also incorporated proinflammatory cytokines (IL17A, IL1B, IL22, IL23, and IFNG) which were upregulated in lesional psoriasis, providing context for the regulation of plakin family members." (PMID 40746860, 2025). "The IL-23–Th17 cell axis is central to psoriasis inflammation development, where IL-23 promotes the differentiation of T cells into IL-17-producing CD4+ T helper cells (Th17), CD8+ cytotoxic T cells (Tc17), and IL-22-producing CD4+ T helper cells (Th22)." (PMID 41376622, 2025). "Similarly, the delivery of recombinant ERDR1 was also able to significantly reduce psoriasiform symptoms and the expression of IL-17, IL-22, and CCL20 in IMQ-induced mouse models of psoriasis." (PMID 40981386, 2025). "Remarkably, our data demonstrated a specific impairment in the differentiation of Tc17 cells within the epidermis of Lztr1-deficient mice, accompanied by decreased expression of T activation-related proteins in psoriasis, such as CTLA-4, PD-1, IL22 and TNF-α 12,38,39." (PMID 41162356, 2025). "In contrast to the other psoriasis markers, the strongest effect on IL-8 expression in the models was observed upon IL-17, not IL-22 treatment." (PMID 40678130, 2025). "Psoriasis is characterized by the dermal and systemic secretion of certain pro-inflammatory cytokines of the Th1 and Th17 cytokine family, such as interferon-γ (IFN-γ), tumor necrosis factor (TNF), interleukin (IL)-6, IL-17, IL-22, and IL-23." (PMID 39775226, 2025). "Additionally, the elevated plasma levels of IL-22 correlate positively with disease severity, as assessed by the PASI score, suggesting its involvement in the pathogenesis of psoriasis." (PMID 40731810, 2025). "In psoriasis, T-cells are overly activated, leading to increased levels of inflammatory cytokines such as tumor necrosis factor-α (TNF-α), interleukin (IL)-17A/C/F, IL-22, and interferon-γ (IFN-γ)." (PMID 38731900, 2024). "Interestingly, incubation of 3D full-thickness skin models with recombinant human IL-17A, IL-22 and TNF-alpha for 5 days leads to hyperkeratosis and parakeratosis, both characteristic of psoriasis." (PMID 37707681, 2024). "We have previously found IL-22 levels to be lower in lesional skin than non-lesional skin in patients with psoriasis and that the levels were unaffected by narrowband ultraviolet B treatment." (PMID 38898675, 2024). "Inhibition of BET proteins reduces the expression of important pro-inflammatory factors (IL-22, IL-17, and RORC) and could represent a potential new treatment for psoriasis." (PMID 38256115, 2024). "IL-17 and IL-22 production by CD3intγδTCRint dermal γδT17 cells was significantly repressed when TL1A availability was limited, suggesting the contribution of TL1A to dermal γδT-cell activation in this psoriasis model." (PMID 38348035, 2024). "This study aimed to investigate the effects of IFN-γ and a cytokine mix (5MIX: IL-1α, IL-17A, IL-22, OsM, and TNF-α) on the antigen-presenting capabilities of keratinocytes, with a specific focus on immune-mediated dermatological conditions such as psoriasis (Ps)." (PMID 39769151, 2024). "Activated plasmacytoid dendritic cells by genetic and/or environmental factors produce large amounts of pro‐inflammatory cytokines [(such as interleukin (IL)‐17, IL‐22, IL‐23, IL‐1β, interferon (IFN)‐γ, and tumor necrosis factor (TNF)‐α], which can then trigger the onset of psoriasis." (PMID 39167035, 2024). "In addition, the 3D TNFF‐α, IL17A and IL22 skin models clearly demonstrated the roles of TNF‐α, IL‐17A and IL‐22 in the formation of the epidermal structure and expression of psoriasis‐related molecules." (PMID 39624730, 2024).
psoriasis (continued). "This study aims to investigate the modulatory effects of IFN-γ and a proinflammatory cytokine mix (5MIX: IL-1α, IL-17A, IL-22, OsM, and TNF-α) on keratinocyte antigen-presenting capacities and their interactions with CD4+ lymphocytes, with a specific focus on their role in psoriasis pathogenesis." (PMID 39769151, 2024). "Psoriasis is a chronic inflammatory immune-mediated dermatosis that involves both Th1 and Th17 cells, with Th1 cells secreting IFN-γ and TNF-α and Th17 cells secreting IL-17, IL-22 and TNF-α." (PMID 38914981, 2024). "Through the synthesis of IL-22 and the subsequent STAT3 activation in K5-promotor transgenic mice engineered to overexpress CD147 in epidermal keratinocytes, epidermal CD147 contributes to the pathophysiology of psoriasis." (PMID 38139173, 2023). "Mice lacking adiponectin develop severe psoriasis-like dermatitis and elevated levels of the Th17-related cytokines IL-17A, IL-17F, and IL-22." (PMID 36675592, 2023). "Psoriasis is currently regarded as a systemic low-grade inflammation supported by a variety of cytokines, chemokines, and other inflammatory mediators including tumor necrosis factor (TNF)-α, interferon (IFN)-γ, interleukin (IL)-17, IL-22, IL-23, and IL-1β." (PMID 37049545, 2023). "Moreover, AOA decreased IL-17A, RORC, and IL-22 secretion by Th17 cells, confirming that AOA is effective in the immune regulation of psoriasis." (PMID 37649889, 2023). "In psoriasis, keratinocytes are considered the main targets of effector cell cytokines such as interleukin (IL)-17 and IL-22; however, they do not participate in the pathogenesis of psoriasis." (PMID 38203230, 2023). "At the ex vivo level, DMF suppressed the gene expression of major cytokines involved in psoriasis, including IFN-γ, IL-17, and IL-22 in mononuclear cells of both psoriasis patients and healthy individuals, inhibiting thus the activity of TH1 and TH17 cells at the lesional skin." (PMID 37108251, 2023). "We found no apparent association between levels of IL-4, IL-12, IL-22, IL-23, IL-35, IL-36 and TGF-β in circulation and the risk of psoriasis." (PMID 37883350, 2023). "Even more important findings demonstrated that CD69 on the skin Tγδ cells controls the secretion of IL-22 by regulating the uptake of L-tryptophan by aromatic amino acid transporter complex LAT1-CD98, which contributes to the development of psoriasis induced by IL-23." (PMID 37892710, 2023). "Hedrick demonstrated that IL-23 did not induce IL-22 in CCR6-/- mouse ears, while triggering IL-22 production in Rag-/- mice, implying that both T and non-T cell-derived IL-22 were involved in IL-23-induced ear swelling in murine psoriasis models." (PMID 35911703, 2022). "Sensing of TNFα and IL22 serum levels using the corresponding receptors and linking their downstream signaling in an AND-gate logic enabled the expression of the anti-inflammatory cytokines IL4 and IL10 to treat psoriasis or prevent its development." (PMID 36225597, 2022). "The activation of the α7nAChR by its agonist PNU-282987 significantly inhibited the STAT3 signaling activation induced by IL-6 and IL-22, indicating that PNU-282987 had the potential to inhibit Th17-mediated inflammation in the skin and alleviate the psoriasis symptom." (PMID 35351863, 2022). "Of considerable interest, the correlation matrix revealed a distinct cytokine panel where cytokines (IFN-γ, IL-18, TNF-α, IL-12B, IL-17A, IL-17F, and IL-22) were positively correlated with each other in psoriasis patients but not in healthy controls." (PMID 36118416, 2022). "Since our findings show that PNU-282987, a selective α7nAChR agonist, can improve the lesioned skin of IMQ-stimulated mice as well as IL-6/IL-22 induced HaCaT cells, we next investigate the effect of Methyllycaconitine citrate (METH), a selective α7nAChR antagonist, on IMQ-induced psoriasis." (PMID 35351863, 2022).